COL11A1 (collagen type XI alpha 1 chain)
Diseases named in the same sentence as COL11A1 in open-access papers (continued):
Sharing a sentence is not in itself a finding about the gene and the disease.
colorectal cancer (20 papers, 2017 to 2026). A primary or metastatic malignant neoplasm that affects the colon or rectum. "Overexpression of COL11A1 is often associated with an aggressive tumor phenotype and a poor prognosis in many solid tumor types, including pancreatic, breast, ovarian, and colorectal cancers." (PMID 38291367, 2024). "The dysregulation in the expression of COL11A1 and mutations alters various critical regulatory pathways to influence the oncogenesis of colorectal cancer in humans." (PMID 33597969, 2021). "In our study, it has been observed that up to 12% mutation that relates to the COL11A1 gene contributes to the development of colorectal cancer with the highest alteration in mucinous adenocarcinoma of colon and rectum." (PMID 33597969, 2021). "The Oncoprint and Mutation tab shows that the COL11A1 gene is altered in 10% of the total 526 patients in TCGA colorectal cancer dataset along with the heatmap for the associated genes." (PMID 33597969, 2021). "Our present study is a maiden attempt to provide a comprehensive knowledge of the various clinical relevance of the COL11A1 gene in the expression profile, methylation, survivability, and mutation in association with the colorectal cancer." (PMID 33597969, 2021). "Therefore, low COL11A1 expression in colorectal cancer patients is correlated with prolonged survival, but high COL11A1 expression in colorectal cancer is associated with poor survival." (PMID 33597969, 2021). "The correlation among the genes associated with COL11A1 gene in colorectal cancer." (PMID 33597969, 2021). "COL11A1 overexpression, measured using mRNA, was first referenced in sporadic colonic carcinomas compared with normal colon tissue of colorectal cancer." (PMID 37760937, 2023). "The COL11A1 gene is overexpressed in many cancer types, including oral cancer and colorectal cancer." (PMID 37707688, 2023). "One study applied bioinformatics method to research the prognostic value of COL11A1 in colorectal carcinoma." (PMID 35669376, 2022). "Particularly for colorectal cancer, previous researchers revealed that the expression of the COL11A1 gene is upregulated up to several folds in the stromal cells of affected colonic mucosa in comparison to the normal tissue." (PMID 33597969, 2021). "A functional network of the interaction among the neighboring genes of the COL11A1 in colorectal cancer displays physical interactions, co-expression, predicted co-localization, pathways, genetic interaction, and shared protein domains." (PMID 33597969, 2021). "KEGG pathways analysis using the DAVID server for top 25 correlated genes of COL11A1 in Colorectal cancer." (PMID 33597969, 2021). "The present study seeks to evaluate the significance of the COL11A1 gene in the progression of colorectal cancer in humans across the various parameters using advanced bioinformatics approaches." (PMID 33597969, 2021). "The results support the inference depicted in the earlier section by demonstrating that COL11A1 expression is higher in the colorectal cancer tissue at different clinical stages than in normal tissue." (PMID 33597969, 2021). "Our study provides several important pieces of evidences on the significance of the COL11A1 gene in the prognosis of human colorectal cancer." (PMID 33597969, 2021). "The KM-plots obtained for the overall survival and disease-free survival show poor prognosis of colorectal cancer i.e., the higher expression of the COL11A1 gene signifies poor survivability." (PMID 33597969, 2021). "Mutations in the COL11A1 gene and/or translational overexpression of COL11A1 protein due to the signaling defects are considered as the essential contributors of carcinogenesis in human colorectal cancer." (PMID 33597969, 2021).
colorectal cancer (continued). "Regarding this, we are in order to work on the cancer cell-lines and the murine model of colorectal cancer for validating the present study and developing efficacious therapeutic strategy by targeting COL11A1 gene." (PMID 33597969, 2021). "The role of the COL11A1 gene in colorectal cancer is significantly upregulated in colorectal cancer." (PMID 33597969, 2021). "For instance, COL11A1 expression was markedly high in colorectal cancer tissue." (PMID 35669376, 2022). "However, further in vitro and in vivo experimental validations are required to determine the efficacy of the COL11A1 gene in the prognosis of colorectal cancer and the development of a therapeutic strategy." (PMID 33597969, 2021). "Collectively all these results reveal that the COL11A1 gene has a positive association and correlation with THBS2, COL10A1, COL5A2, and COL1A2 to upregulate the gene expression to induce the development of colorectal cancer." (PMID 33597969, 2021). "Therefore, our experimental data firmly claims the candidature of the COL11A1 gene as a potential biomarker for the prognosis of colorectal cancer and opens new areas of research for the diagnosis and development of appropriate therapeutic strategies." (PMID 33597969, 2021). "Collectively all these experimental data clearly reveal that the COL11A1 gene along with its associated THBS2, COL10A1, COL5A2, and COL1A2 might serve as a prognostic biomarker for colorectal cancer." (PMID 33597969, 2021). "To identify the molecular mechanism underlying the ETV4-mediated EMT and metastasis in colorectal cancer cells, we next leveraged our RNA-seq data and a series of key downstream genes associated with EMT were further confirmed, including MER3, MSX1, LOXL2, THRB, WISP2, COL11A1, ADRB2 and E2F2." (PMID 41281746, 2025). "Similarly, COL11A1 levels are notably higher in colorectal cancer tissues than in normal tissues." (PMID 39845732, 2025). "It has been reported that COL11A1 may be a potential prognostic marker for colorectal cancer." (PMID 39845732, 2025). "All these data collectively indicate that human colorectal cancer samples display significantly higher expression of COL11A1 mRNA in comparison to normal colon and rectum tissues, indicating COL11A1 could have a crucial role in the neoplastic transformation of colorectal cancer." (PMID 33597969, 2021). "In addition, our study also aggregates all the available discrete data to identify the significance of the COL11A1 gene as a prognosis biomarker for colorectal cancer which may be useful in designing future research for the conception of appropriate therapeutic strategies." (PMID 33597969, 2021). "A previous pan-cancer single cell analysis of ovarian, lung, and colorectal cancer, showed that COMP, COL10A1, COL11A1, and MMP1 all have higher expression in CAFs26." (PMID 34732773, 2021). "The PathwayMapper tab in cBioPortal servers shows the alteration frequency of COL11A1, THBS2, COL10A1, COL5A2, and COL1A2 over the various pathways on the colorectal cancer dataset using a white to red color scale where the more frequently altering gene shows greater intensity of the red color." (PMID 33597969, 2021). "The PPI networks indicate the RAB31, COL1A1, COL1A2, COL3A1, COL11A1, and VCAN as the most important protein network that likely to be connected and show betweenness among themselves to significantly promote the prognosis of colorectal cancer." (PMID 33597969, 2021). "Further analyses of the mRNA expression profiles of the COL11A1 gene in normal and transformed tissue in ONCOMINE server reveal significant upregulation of COL11A1 mRNA in both the subtypes of cancer datasets i.e., TCGA colorectal cancer and Kaiser colon cancer." (PMID 33597969, 2021).
type II Stickler syndrome (19 papers, 2012 to 2025). "The variant is a SNP located in a collagen type XI gene (COL11A1) in which pathogenic variants are known to cause syndromic conditions in humans; Stickler Syndrome Type II being the most analogous to the OES MOD phenotype described here." (PMID 38153936, 2023). "In humans, variants in the COL11A1 gene are associated with Stickler syndrome type II, also dominantly inherited." (PMID 38153936, 2023). "A smaller proportion of AD cases are caused by heterozygous pathogenic variants in COL11A1 (Stickler Syndrome Type II [STL2]), and COL11A2 (Otospondylomegaepiphseal dysplasia, AD [OSMEDA], formerly known as Non-Ocular Stickler Syndrome)." (PMID 32867104, 2020). "In a recent case report, a child with Stickler syndrome type II was found to have a novel missense mutation in COL11A1." (PMID 30809385, 2019). "Stickler syndrome type II is caused by COL11A1 gene mutations." (PMID 37082197, 2023).
myopia (18 papers, 2011 to 2026). "Mutations in COL2A1 and COL11A1 are associated with early-onset high myopia; however, myopia of ≥−10D was more common in COL2A1 than in COL11A1 (40% vs. 19%)." (PMID 34501218, 2021). "Seventy-five percent of cases (6/8) had a cleft palate or uvula bifida (3/3 with COL11A1 variants, 3/5 with COL11A2 variants), and all three cases with COL11A1 variants had congenital myopia." (PMID 31427586, 2019). "Mutations in the COL11A1 gene are also associated with the autosomal dominant type II Stickler syndrome, which features a variable phenotype, including visual disturbances such as type 2 vitreous anomaly, childhood-onset myopia, glaucoma, cataracts and retinal detachment." (PMID 28331057, 2017). "Of these, family 6 with tooth agenesis and family 11 with high myopia and congenital deafness, had additional variants in WNT10A and COL11A1, respectively, accounting for their extraocular features." (PMID 40301690, 2025). "The most common pathogenic genes responsible for high myopia with RRD were COL2A1 (10.0%, 4/40) and COL11A1 (5.0%, 2/40) and VCAN (5.0%, 2/40)." (PMID 40270540, 2025). "Thirty-two (32/42, 76%) probands had high myopia in total, 21 (21/27, 78%) of whom had COL2A1 mutations, and 5 (5/8, 63%) had COL11A1 mutations." (PMID 32756486, 2020). "The phenotypic subset associated with myopia (n = 130) was found to represent a set of 119 unique genes since 7 genes (COL2A1, COL11A1, FBN1, LTBP2, POMT1, POMT2, POMGNT1) had two or more associated phenotypes, leading to 11 duplicates." (PMID 29346494, 2018). "In summary, we examined using a DNA pooling approach tag SNPs from four candidate genes (COL11A1, COL18A1, FBN1, and PLOD1) selected because pathogenic mutations in these genes cause disease syndromes that have myopia, usually high myopia, as one of the common presenting clinical features." (PMID 21527992, 2011). "In conclusion, common polymorphisms in these four candidate genes (COL11A1, COL18A1, FBN1, and PLOD1) were unlikely to play important roles in the genetic susceptibility to high myopia." (PMID 21527992, 2011). "Therefore, we propose that SOX11 may directly or indirectly affect proteins with strong links to high myopia, such as COL9A1, COL2A1, and COL11A1, by affecting the expression or function of SOX4, ultimately causing the clinical phenotype of eoHM and dystrophy of cone-rod cells in CSS9 individuals." (PMID 40933692, 2025).
lung adenocarcinoma (17 papers, 2018 to 2026). A carcinoma that arises from the lung and is characterized by the presence of malignant glandular epithelial cells. "Using the GEPIA database, Kaplan-Meier Plotter database, GSE72094, GSE75037, GSE32863, and our immunohistochemistry experiment data, we confirmed that COL11A1 overexpresses in lung adenocarcinoma and that high expression of COL11A1 is associated with a poor prognosis." (PMID 38649961, 2024). "COL11A1 may be expressed and secreted by cancer-associated fibroblasts, and a high expression of COL11A1 may result in T cell exhaustion in the tumor microenvironment of lung adenocarcinoma." (PMID 38649961, 2024). "For instance, COL5A1 has been implicated in promoting mechanical stress and therapy resistance in lung adenocarcinoma, while COL11A1 activates CAFs through the TGF-β/NF-κB/IGFBP2 signaling axis in various solid tumors." (PMID 40574832, 2025). "FGF14 has been confirmed to inhibit tumor growth in lung adenocarcinoma, and this effect can be achieved by the inhibition of COL11A1 and MUC16 proteins by FGF14." (PMID 38040694, 2023). "High CSF proportion was associated with poor prognosis in bladder cancer (BCa) and lung adenocarcinoma (LUAD), and IHC staining of COL11A1 confirmed their specific expression in tumor stroma in clinical BCa samples." (PMID 36744260, 2023). "Herein, we aimed to explore the function of COL11A1 and its upstream regulators in lung adenocarcinoma (LUAD)." (PMID 35892083, 2022). "Our group first showed that integrin α11 among five other genes including COL11A1 (collagen type XI) was differentially expressed in lung adenocarcinoma as compared to normal lung." (PMID 35378690, 2022). "Fibroblast growth factor-14 (FGF-14) is downregulated in lung adenocarcinoma patient samples, and its overexpression in the lung adenocarcinoma cell line A549 results in downregulation of COL11A1 expression." (PMID 35847935, 2022). "Herein, we aimed to further investigate the upstream regulator of COL11A1 in lung adenocarcinoma (LUAD)." (PMID 35892083, 2022). "COL11A1 is involved in the extracellular matrix activities of lung adenocarcinoma." (PMID 38649961, 2024). "Using the TISCH database, we found that COL11A1 is mainly expressed by cancer-associated fibroblasts in the tumor microenvironment rather than by lung adenocarcinoma cells." (PMID 38649961, 2024). "COL11A1 has a genetic alteration frequency of 22% in patients with lung adenocarcinoma." (PMID 38649961, 2024). "A high expression of COL11A1 may result in T cell exhaustion in the TME of lung adenocarcinoma." (PMID 38649961, 2024). "FGF-14 is downregulated in lung adenocarcinoma patient samples, and the overexpression of FGF-14 in the lung adenocarcinoma cell line A549 results in downregulation of COL11A1 expression." (PMID 33668097, 2021). "Finally, we found that COL11A1 is positively correlated with HAVCR2(TIM3), CD274 (PD-L1), CTLA4, and LAG3 in lung adenocarcinoma." (PMID 38649961, 2024). "Additionally, COL11A1 was shown to be significantly expressed in both NSCLC and lung adenocarcinoma, and it has been shown to encourage the growth, migration, and invasion of NSCLC cell lines in vitro." (PMID 37476379, 2023). "Moreover, supernatant media from lung adenocarcinoma cells (A549) strongly induced ITGA11 and COL11A1 expression, compared to that from normal epithelial cells (BEAS‐2B), without affecting expression of integrin α5 or β1 in HFL‐1." (PMID 33682233, 2021).
hearing loss (16 papers, 2012 to 2025). "Recently, a pathogenic variant in COL11A1 in a large family has been linked to non-syndromic hearing loss." (PMID 35736209, 2022). "COL11A1: ID8 has hearing loss, left-sided SSCD, and heterozygous missense variants in two genes known for AD nonsyndromic hearing loss, namely COL11A1 (MIM 120280; 1p21.1) and TECTA (MIM 602574; 11q23.3)." (PMID 33924653, 2021). "The remaining gene variants in CEACAM16, COL11A1, COL9A2, DIAPH1, TCOF1 were tested for segregation with the hearing loss phenotype in the extended family." (PMID 35292975, 2022). "Several collagen genes (COL1A1, COL1A2, COL2A1, COL4A3, COL4A4, COL4A5, COL11A1, and COL11A2) are associated with hereditary syndromic hearing loss." (PMID 33848312, 2021). "Overall, mutations in COL11A1 (82.5%) and COL11A2 (94.1%) seem to be more frequently associated with hearing impairment than mutations in COL2A1 (52.2%)." (PMID 23110709, 2012). "Potential causative variants were identified in genes associated with nonsyndromic hearing loss (CIB2, COL11A1, ILDR1, MYO15A, TMPRSS3, and WFS1), nonsyndromic hearing loss or Usher syndrome (CDH23, MYO7A, PCDH15, and USH2A), and other syndromic forms of hearing loss (CHD7, OPA1, and SPTLC1)." (PMID 34837038, 2022). "Mutations in COL11A1 and COL11A2 have been shown to cause nonsyndromic hereditary hearing loss." (PMID 33848312, 2021). "The COL11A1 and COL11A2 proteins have been reported in the developing mouse cochlear and in a mouse model, COL11A1 haploinsufficiency does not cause significant hearing loss, whereas in humans haploinsufficiency has been reported to cause mild hearing loss." (PMID 32901364, 2021).
gastric cancer (14 papers, 2015 to 2025). A primary or metastatic malignant neoplasm involving the stomach. "Recent single-cell analyses of gastric cancer highlight COL11A1-positive fibroblasts as a tumor-specific CAF subtype producing ECM components associated with chemoresistance and immune evasion." (PMID 40906383, 2025). "A previous study showed that seven collagen genes (COL1A2, COL4A1, COL6A2, COC6A1, COL4A2, and COL11A1) were highly expressed in gastric cancer tissues, consistent with our findings." (PMID 39220121, 2024). "In our study we focused on the expression changing level of OLFM4 and COL11A1 in Iranian patients to identify role of these genes in gastric cancer progression." (PMID 29511474, 2017). "In most cases, OLFM4 and COL11A1 are found to be up-regulated in many types of human cancers including gastric cancer." (PMID 29511474, 2017). "Due to limited information on these genes and to a better understanding of common biomarkers associated with cancer of the digestive tract routes, we aim to evaluated expression level of Olfactomedin4 (OLFM4) and (pro)collagen11A1/COL11A1 genes in people with gastric cancer in Iran." (PMID 29511474, 2017). "As for COL11A1, a previous study suggested it could be used for differentiating the malignant lesions from premalignant tissues in stomach cancer based on 42 tissues samples, and our result further supports their conclusions though more studies are still warranted." (PMID 35910202, 2022). "Steady-state fibroblasts in cancer were described to progress towards activated CAFs expressing for instance CTHRC1, and COL11A1, similar to the differentiation trajectory we found for F13-CTHRC1 activated fibroblasts in gastric cancer." (PMID 36550535, 2022). "On the other hand, COL11A1 gene expression level in the early stages of gastric cancer is not much increased." (PMID 29511474, 2017). "The top up-regulated gene with the highest magnitude of differential expression in both figures, COL11A1, has been reported to be over-expressed in recurrent non-small cell lung cancer and in gastric cancer tissues and to promote cell proliferation, migration, invasion and drug resistance." (PMID 29268695, 2017). "Moreover, expression of COL5A2 and COL11A1 was associated with colorectal carcinogenesis showing that COL5A2 was co-expressed with COL11A1 in colorectal tumor samples, but not in normal colon epithelia; however, it remains unknown which miRNA(s) regulate their expression in gastric cancer." (PMID 25860484, 2015).